PLCH1 (phospholipase C eta 1)
Description:
The production of the second messenger molecules diacylglycerol (DAG) and inositol 1,4,5-trisphosphate (IP3) is mediated by calcium-activated phosphatidylinositol-specific phospholipase C enzymes.
Synonyms: PLC-L3; KIAA1069; PLCL3; MGC117152; DKFZp434C1372; PLCeta1; HPE14; PLC eta 1
Tractability: Antibody: its Gene Ontology location is reachable by antibodies, with high confidence. PROTAC: ubiquitination databases record sites on it; its protein half-life has been measured.
Gene: Protein-coding gene on chromosome 3 (155,375,580 to 155,745,085, reverse strand). Ensembl gene ENSG00000114805.
Subcellular location: Cytoplasm; Membrane
Subcellular location (Human Protein Atlas): Vesicles
Pathways (Reactome):
Metabolism: Synthesis of IP3 and IP4 in the cytosol
Gene Ontology:
Molecular function: phosphatidylinositol-4,5-bisphosphate phospholipase C activity; calcium ion binding; phospholipase C activity; phosphoric diester hydrolase activity
Biological process: phosphatidylinositol-mediated signaling; phosphatidylinositol metabolic process; release of sequestered calcium ion into cytosol; intracellular signal transduction; lipid metabolic process; signal transduction
Cellular component: cytoplasm; membrane; plasma membrane
Genetic constraint (gnomAD): Loss-of-function variants: 36 observed, 72.72 expected, observed/expected ratio (o/e) 0.5, 90% interval 0.38 to 0.65. The upper end of that interval is the gene's LOEUF score, 0.65, which puts it in group 2 of 6, group 1 being the genes least tolerant of losing a copy. Missense variants: 1,400 observed, 1,716.4 expected, observed/expected ratio (o/e) 0.82, 90% interval 0.78 to 0.85. Synonymous variants: 587 observed, 628.74 expected, observed/expected ratio (o/e) 0.93, 90% interval 0.87 to 1.
Homologues: Orthologues: chimpanzee PLCH1 (98% identical), macaque PLCH1 (96% identical), rabbit PLCH1 (88% identical), pig PLCH1 (88% identical), mouse Plch1 (85% identical), rat Plch1 (84% identical), guinea pig PLCH1 (84% identical), tropical clawed frog plch1 (62% identical), dog PLCH1 (56% identical), zebrafish plch1 (53% identical), Caenorhabditis elegans pll-1 (18% identical), Caenorhabditis elegans plc-3 (17% identical), and 3 more. Paralogues in human: PLCH2 (42% identical), PLCL1 (21% identical), PLCL2 (21% identical), PLCE1 (19% identical), PLCD4 (18% identical), PLCG1 (18% identical), PLCG2 (18% identical), PLCD1 (17% identical), PLCB4 (17% identical), PLCB3 (16% identical), PLCB2 (16% identical), PLCD3 (16% identical), and 2 more.
Diseases named in the same sentence as PLCH1 in open-access papers:
PLCH1 is named in the same sentence as 19 diseases in open-access papers, as found by Europe PMC text mining. Sharing a sentence is not in itself a finding about the gene and the disease. The quoted sentences say what the papers report.
breast carcinoma (3 papers, 2019 to 2025). "Our bioinformatics analysis suggested that PLCH1 expression is significantly linked to proliferation-related signaling pathways in breast cancer." (PMID 40519297, 2025). "The integration of PLCH1 expression into prognostic models enhances their predictive accuracy, highlighting its potential as a critical biomarker for risk stratification and individualized treatment planning in breast cancer." (PMID 40519297, 2025). "PLCH1 was overexpressed in breast cancer and was associated with worse patient outcomes." (PMID 40519297, 2025). "PLCH1 holds significant potential as both a diagnostic and therapeutic target for breast cancer." (PMID 40519297, 2025). "Next, the prognostic value of PLCH1 expression in breast cancer patients was further assessed using Kaplan-Meier survival analyses." (PMID 40519297, 2025). "Functional studies revealed that PLCH1 was highly expressed in breast cancer cell lines, and PLCH1 knockdown significantly inhibited cell proliferation, induced cell cycle arrest, and reduced cyclin-dependent kinase 1 (CDK1) expression in BT-474 cells." (PMID 40519297, 2025). "The identification of PLCH1 as a key player in breast cancer biology not only fills a significant gap in understanding this underexplored gene but also highlights its potential as both a prognostic biomarker and therapeutic target." (PMID 40519297, 2025). "PLCH1 was significantly overexpressed in various cancers, including breast cancer, compared to normal tissues." (PMID 40519297, 2025). "This relationship underscores the potential role of PLCH1 as a marker of genomic instability in breast cancer." (PMID 40519297, 2025). "In this study, a comprehensive analysis of publicly available datasets revealed that PLCH1 was significantly overexpressed in breast cancer tissues compared to normal tissues." (PMID 40519297, 2025). "The strong correlations between PLCH1 expression and the activity of these pathways highlight its potential as a central regulator in breast cancer biology and a promising therapeutic target." (PMID 40519297, 2025). "Collectively, these findings reveal that PLCH1 is a key player in molecular networks, genomic instability, and drug resistance in breast cancer." (PMID 40519297, 2025). "This study highlights the clinical significance of PLCH1 as both a prognostic biomarker and a therapeutic target in breast cancer." (PMID 40519297, 2025). "Further analysis confirmed that PLCH1 expression was markedly elevated in breast cancer tissues compared to normal tissues (P = 1.15e-23), emphasizing its importance in breast cancer pathogenesis and its relevance as a target for future investigation." (PMID 40519297, 2025). "Given the importance of PLCH1 in breast cancer prognosis, a prognostic model incorporating PLCH1 expression and clinicopathological features was developed and validated." (PMID 40519297, 2025). "Building on our observation that PLCH1 knockdown inhibits breast cancer cell proliferation, its role in regulating the cell cycle and apoptosis in BT-474 cells was further investigated." (PMID 40519297, 2025). "Stratifying breast cancer samples by clinical and molecular characteristics revealed significant differences in PLCH1 expression." (PMID 40519297, 2025). "Subsequently, the mutation profiles of key cancer-related genes were analyzed in breast cancer samples with low and high PLCH1 expression levels." (PMID 40519297, 2025). "This study is the first to demonstrate that PLCH1 promotes breast cancer cell proliferation and contributes to tumor progression, thus filling a significant gap in the research." (PMID 40519297, 2025). "In summary, this study provides compelling evidence that PLCH1 plays a critical role in breast cancer progression, particularly in HER2-positive, ER- positive, and PR-positive subtypes, where its overexpression is associated with poor clinical outcomes." (PMID 40519297, 2025).
breast carcinoma (continued). "Knockdown of PLCH1 leads to cell cycle arrest and induces apoptosis, highlighting its potential as a therapeutic target in breast cancer." (PMID 40519297, 2025). "Its role in promoting cell proliferation via the ERK1/2-EGR1 axis highlighted PLCH1 as a potential therapeutic target for breast cancer." (PMID 40519297, 2025). "In future, larger prospective clinical cohorts with advanced in vivo models will be conducted to validate these findings and explore the therapeutic potential of targeting PLCH1 in breast cancer." (PMID 40519297, 2025). "Although the role of the PLC family in breast cancer has been extensively studied, the role of PLCH1 in breast cancer remains largely unexplored." (PMID 40519297, 2025). "Additionally, an in-depth analysis of clinicopathological features identified significant correlations between PLCH1 expression and key markers of breast cancer, including ER, PR, and HER2." (PMID 40519297, 2025). "Knockdown of PLCH1 using two specific siRNAs (si-PLCH1#1 and si-PLCH1#3) in BT-474 breast cancer cells significantly reduced the expression of p-ERK and early growth response 1 (EGR1), key components of the ERK signaling pathway, as demonstrated by Western blot analysis." (PMID 40519297, 2025). "Our results revealed significantly upregulated PLCH1 mRNA expression in all breast cancer cell lines (MDA-MB-231, MDA-MB-468, BT-474, SKBR-3, and MCF-7) compared to normal breast epithelial cells MCF-10A (P < 0.01 to P < 0.0001), with the highest expression observed in SKBR-3 and BT-474 cells." (PMID 40519297, 2025). "Notably, PLCH1 was particularly overexpressed in breast cancer compared to normal breast tissues, suggesting a potential oncogenic role in driving tumor initiation and progression." (PMID 40519297, 2025). "Inhibiting PLCH1 expression could be a viable strategy to suppress breast cancer progression, particularly in aggressive subtypes." (PMID 40519297, 2025). "Cells treated with si-PLCH1#1 and si-PLCH1#3 exhibited significantly reduced proliferation compared to the control group on days 3, 4, and 5 (P < 0.001, P < 0.0001), indicating that PLCH1 is essential for sustaining breast cancer cell growth." (PMID 40519297, 2025). "Notably, in HER2-positive breast cancer patients, high PLCH1 expression was also correlated with significantly reduced OS, RFS, and DMFS." (PMID 40519297, 2025). "These pathways regulate critical processes in tumor progression, including cell proliferation, apoptosis suppression, and DNA repair, suggesting that PLCH1 may contribute to breast cancer development by modulating these pathways." (PMID 40519297, 2025). "Collectively, these findings suggest that PLCH1 may serve as a potential therapeutic target in breast cancer." (PMID 40519297, 2025). "PLCH1 expression was strongly correlated with the expression of estrogen receptor (ER), progesterone receptor (PR), and human epidermal growth factor receptor 2 (HER2) in breast cancer tissues, further linking PLCH1 to poor prognosis and adverse patient outcomes." (PMID 40519297, 2025). "Additionally, our results underscore the potential of targeting PLCH1 as a novel therapeutic strategy, particularly for aggressive breast cancer subtypes with limited treatment options." (PMID 40519297, 2025). "Given the established roles of other PLC isoforms in breast cancer progression, understanding the contribution of PLCH1 to tumor biology may provide novel insights into its potential as a therapeutic target, particularly in aggressive subtypes with poor prognoses." (PMID 40519297, 2025). "The results showed significantly higher PLCH1 expression in several cancer types, including acute myeloid leukemia (AML), lung cancer, breast cancer, and pancreatic cancer." (PMID 40519297, 2025). "However, the precise role of PLCH1 in breast cancer remains unclear." (PMID 40519297, 2025).
breast carcinoma (continued). "Our analysis of clinicopathological characteristics revealed a significant association between PLCH1 expression and receptor status in breast cancer, with elevated PLCH1 levels observed in HER2-positive, ER-positive, and PR-positive breast cancer patients." (PMID 40519297, 2025). "In summary, these findings highlight that PLCH1 plays a crucial role in promoting ERK signaling, inhibiting apoptosis, and facilitating cell cycle progression in breast cancer cells." (PMID 40519297, 2025). "Cellular studies further validated these results, showing significantly higher PLCH1 expression in HER2-positive BT-474 and SKBR3 cell lines compared to other breast cancer cell lines." (PMID 40519297, 2025). "Tumors positive for key breast cancer markers, including ER-positive (ER+), BRCA protein expression-positive (BR+), and HER2-negative (HER2-), exhibited significantly higher PLCH1 expression compared to their respective negative counterparts (ER−, BR−, HER2−) (all P < 0.0001)." (PMID 40519297, 2025).
chronic myeloid leukemia (2 papers, 2023 to 2025). "For instance, in chronic myeloid leukemia, the upregulation of PLCH1 has been confirmed to be associated with cellular resistance to tyrosine kinase inhibitors." (PMID 40519297, 2025).
autism spectrum disorder (1 paper, 2022). A spectrum of developmental disorders that includes autism, and Asperger syndrome. "In particular, the enrichment of autism spectrum disorder genetic risk in L4 PLCH1 and L6 TLE4 cells can only be identified in vestigial enhancers." (PMID 35419551, 2022).
congenital toxoplasmosis (1 paper, 2020). Toxoplasma infection that is present from birth. "However, a recent paper reported that PLCH1 expression can be modulated during toxoplasma gondii infection and this finding is interesting if we consider that congenital toxoplasmosis can be a cause of preterm birth." (PMID 32708910, 2020).
invasive breast carcinoma (1 paper, 2025). A carcinoma that infiltrates the breast parenchyma. "Our study demonstrated that elevated PLCH1 expression was closely associated with reduced OS and DFS in postoperative patients with invasive breast cancer." (PMID 40519297, 2025). "IHC staining further confirmed these findings, demonstrating markedly elevated levels of PLCH1 positivity in cancerous tissues from patients with invasive breast carcinoma." (PMID 40519297, 2025).
ovarian carcinoma (1 paper, 2025). A malignant neoplasm originating from the surface ovarian epithelium. "Additionally, studies in ovarian cancer have found that elevated PLCH1 expression can modulate the proliferation and apoptosis of cancer cells." (PMID 40519297, 2025).
prostate carcinoma (1 paper, 2025). A carcinoma that arises from epithelial cells of the prostate gland. "Furthermore, high expression levels of PLCH1 have been linked to various single nucleotide polymorphisms, which may influence prostate-specific antigen levels, thereby affecting the risk and prognosis of prostate cancer." (PMID 40519297, 2025).
small cell lung carcinoma (1 paper, 2022). Small cell lung cancer (SCLC) is a highly aggressive malignant neoplasm, accounting for 10-15% of lung cancer cases, characterized byrapid growth, and early metastasis.
squamous cell carcinoma (1 paper, 2025). A carcinoma arising from squamous epithelial cells. "Specific single nucleotide polymorphisms at the PLCH1 locus has been associated with an increased risk of squamous cell carcinoma in the Chinese non-smoking populations, suggesting that PLCH1 may be related to cancer susceptibility." (PMID 40519297, 2025).
cancer (3 papers, 2020 to 2025). A tumor composed of atypical neoplastic, often pleomorphic cells that invade other tissues. "Univariate Cox regression demonstrated that PLCH1 expression (P = 0.027, HR = 1.142) was a significant risk factor for OS, along with age and cancer stage." (PMID 40519297, 2025). "Phospholipase C η1 (PLCH1), a member of the phospholipase C superfamily, has been implicated in the development of multiple cancers." (PMID 40519297, 2025). "Quantitative analysis confirmed significantly higher PLCH1 protein levels in cancer cell lines compared to MCF-10A (P < 0.05 to P < 0.0001)." (PMID 40519297, 2025). "The inhibitory effect of PLCH1 suppression on cancer cell growth further emphasizes its potential as a therapeutic target, particularly for subtypes characterized by high PLCH1 expression." (PMID 40519297, 2025). "Stratification of patients based on PLCH1 expression levels, age, cancer stage, tumor size, metastasis status, and lymph node involvement revealed that high PLCH1 expression was significantly associated with advanced stage, metastasis, and lymph node involvement." (PMID 40519297, 2025). "Collectively, these results highlight the potential of PLCH1 not only as a marker for cancer progression and prognosis but also as a promising therapeutic target due to its association with oncogenic signaling, molecular characteristics, and epigenetic regulation." (PMID 40519297, 2025). "Interestingly, the most significantly upregulated genes in Ppm1dT/+ AML (Zbed3, Runx3, Marcks, Extl3, Pcbp4, Igf2bp3, Plch1, and Gdf6) were previously associated with AML and cancer progression." (PMID 37709843, 2023).
tumor (2 papers, 2019 to 2025). "These associations suggest that PLCH1 may play a crucial role in tumor progression, particularly in hormone- and growth factor-driven subtypes." (PMID 40519297, 2025). "A nomogram was constructed to provide individualized survival predictions by integrating PLCH1 expression, tumor size, metastasis status, lymph node involvement, age, and stage into a scoring system." (PMID 40519297, 2025). "Next, the role of PLCH1 in regulating tumor-related signaling pathways was further explored using a pathway enrichment analysis of KEGG signaling pathways." (PMID 40519297, 2025). "Quantitative analysis confirmed that PLCH1 expression was significantly higher in tumor tissues compared to adjacent normal tissues (P < 0.0001)." (PMID 40519297, 2025). "The integration of PLCH1 expression into functional and clinical models may provide valuable insights into tumor biology and aid in the development of personalized therapeutic strategies." (PMID 40519297, 2025). "By integrating bioinformatics analyses, IHC staining of patient tissues, and in vitro functional studies, we demonstrated that PLCH1 promoted tumor cell proliferation and survival by regulating cell cycle proteins (CDK1 and Cyclin B1) and the ERK-EGR1 signaling pathway." (PMID 40519297, 2025). "First, although our findings were validated through bioinformatics analysis, IHC staining, and in vitro experiments, the lack of in vivo models restricted our ability to comprehensively assess the role of PLCH1 in tumor growth, metastasis, and therapy resistance." (PMID 40519297, 2025). "This suggests that PLCH1 participates in a broad molecular network that may influence tumor progression and key signaling pathways." (PMID 40519297, 2025). "In addition, PLCH1 expression also correlated strongly with KEGG_EGF_EGFR_RAS_PI3K_SIGNALING_PATHWAY (R = 0.32, P < 2.22e-16) and the KEGG_CELL_CYCLE pathway (R = 0.47, P < 2.22e-16), underscoring its potential role in promoting tumor cell proliferation." (PMID 40519297, 2025). "Taken together, these results indicate that PLCH1 is closely linked to the activation of key oncogenic pathways, including EGFR-MAPK signaling, cell cycle regulation, and DNA repair processes, all of which play vital roles in tumor progression and genomic stability." (PMID 40519297, 2025). "Strong PLCH1 staining was observed in tumor tissues, while adjacent normal tissues showed little to no staining." (PMID 40519297, 2025). "Preliminary evidence indicates that PLCH1 may regulate key signaling pathways, such as the extracellular signal-regulated kinases 1 and 2 (ERK1/2) pathway, which are crucial for tumor proliferation and survival." (PMID 40519297, 2025). "Mechanistically, PLCH1 silencing downregulated early growth response 1 (EGR1) expression by suppressing the extracellular signal-regulated kinases 1 and 2 (ERK1/2) signaling pathway, impairing tumor cell proliferation." (PMID 40519297, 2025). "PLCH1 expression showed a strong positive correlation with EGFR-related pathways, including KEGG_TGFA_EGFR_PLCG_PKC_SIGNALING_PATHWAY (R = 0.35, P < 2.22e-16) and KEGG_EGF_EGFR_PLCG_ERK_SIGNALING_PATHWAY (R = 0.27, P < 2.22e-16), which are crucial for tumor cell proliferation and migration." (PMID 40519297, 2025).
PLCH1 also shares sentences with these, for which no sentence is quoted: lung carcinoma (2 papers); acute myeloid leukemia (1); adenocarcinoma (1); hepatocellular carcinoma (1); Obesity (1); pancreatic cancer (1); periodontitis (1); type 2 diabetes (1).